WDR19 (WD repeat domain 19)
Description:
As component of the IFT complex A (IFT-A), a complex required for retrograde ciliary transport and entry into cilia of G protein-coupled receptors (GPCRs), it is involved in cilia function and/or assembly. Essential for functional IFT-A assembly and ciliary entry of GPCRs. Associates with the BBSome complex to mediate ciliary transport (By similarity).
Synonyms: IFT144; KIAA1638; Pwdmp; FLJ23127; ORF26; DYF-2; Oseg6; NPHP13; FAP66; CFAP66; ATD5; CED4; SPGF72; SRTD5
Tractability: Antibody: its Gene Ontology location is reachable by antibodies, with medium confidence. PROTAC: ubiquitination databases record sites on it; its protein half-life has been measured.
Gene: Protein-coding gene on chromosome 4 (39,182,494 to 39,285,810, forward strand). Ensembl gene ENSG00000157796.
Subcellular location: Cell projection, cilium; Cytoplasm, cytoskeleton, cilium basal body; Cell projection, cilium, photoreceptor outer segment; Cell projection, cilium, flagellum
Subcellular location (Human Protein Atlas): Mid piece; Nucleoplasm; Basal body; Centrosome; Cytosol; Principal piece
Pathways (Reactome):
Organelle biogenesis and maintenance: Intraflagellar transport
Signal Transduction: Hedgehog 'off' state
Gene Ontology:
Molecular function: protein binding; protein carrier chaperone
Biological process: intraciliary anterograde transport; intraciliary retrograde transport; protein localization to ciliary membrane; protein localization to non-motile cilium; protein-containing complex assembly; cilium assembly; cilium organization; protein localization to membrane
Cellular component: intraciliary transport particle A; sperm midpiece; sperm principal piece; ciliary tip; cilium; motile cilium; non-motile cilium; photoreceptor connecting cilium; photoreceptor outer segment
Genetic constraint (gnomAD): Loss-of-function variants: 99 observed, 140.39 expected, observed/expected ratio (o/e) 0.71, 90% interval 0.6 to 0.83. The upper end of that interval is the gene's LOEUF score, 0.83, which puts it in group 3 of 6, group 1 being the genes least tolerant of losing a copy. Missense variants: 1,357 observed, 1,490.8 expected, observed/expected ratio (o/e) 0.91, 90% interval 0.87 to 0.95. Synonymous variants: 467 observed, 497.06 expected, observed/expected ratio (o/e) 0.94, 90% interval 0.87 to 1.01.
Gene-disease validity (ClinGen):
ClinGen rates the evidence that WDR19 causes each of these diseases.
ciliopathy (autosomal recessive): Definitive. A genetic disorder of the cellular cilia or the cilia anchoring structures, the basal bodies, or of ciliary function.
Homologues: Orthologues: chimpanzee WDR19 (99% identical), macaque WDR19 (98% identical), dog WDR19 (93% identical), pig WDR19 (91% identical), rat Wdr19 (90% identical), rabbit WDR19 (90% identical), mouse Wdr19 (90% identical), guinea pig WDR19 (89% identical), tropical clawed frog wdr19 (79% identical), zebrafish wdr19 (76% identical), Drosophila melanogaster Oseg6 (41% identical), Caenorhabditis elegans dyf-2 (40% identical).
Diseases named in the same sentence as WDR19 in open-access papers:
WDR19 is named in the same sentence as 52 diseases in open-access papers, as found by Europe PMC text mining. Sharing a sentence is not in itself a finding about the gene and the disease. The quoted sentences say what the papers report.
ciliopathies (12 papers, 2014 to 2025). "On day 18, exceptionally high activation of Shh was notable even in the WDR19:C.878G>A variant, indicating that ciliopathy pathogenesis becomes more prominent as differentiation progresses." (PMID 41141533, 2025). "Pathogenic variants in the WDR19/NPHP13 gene were first reported in Caroli disease associated with nephronophthisis-related ciliopathies (NPHP-RC), an autosomal recessive cystic kidney disorder." (PMID 35741793, 2022). "Loss-of-function mutations in the WD repeat domain of the WDR19 gene lead to severe ciliopathies in humans." (PMID 32407316, 2020). "Given the glomerular sclerosis, glomerular cysts, and IgA nephropathy–like pathology observed in some of the patients with WDR19 mutations, it is crucial to expand our understanding of how ciliary dysfunction impacts podocyte function and glomerular integrity in ciliopathies." (PMID 41141533, 2025). "Mutations in WDR19 have been associated with a broad spectrum of ciliopathies, such as Sensenbrenner syndrome (cranioectodermal dysplasia), Jeune syndrome, Senior-Loken syndrome (nephronophthisis and pigmentary retinopathy), and nonsyndromic asthenoteratospermia." (PMID 38062428, 2023). "In conclusion, this study provides insights into the role of WDR19 in kidney development and the pathogenesis of ciliopathies in general." (PMID 41141533, 2025). "The present study reports four prenatal cases of SRPS/SRTD as implicated by ultrasound findings, which provide useful information regarding the novel variants of ciliopathies-associated genes DYNC2H1, IFT172, and WDR19." (PMID 38062428, 2023). "Four different homozygous single nucleotide variants (SNVs) were detected in 4 known ciliopathy genes (TMEM231,TMEM138,WDR19 andBBS9) and were confirmed by Sanger sequencing." (PMID 34354814, 2021). "Collectively, our case series provide information regarding the novel variants of ciliopathies-associated genes DYNC2H1, IFT172, and WDR19, and emphasize the importance of both clinical and genetic findings in the setting of prenatal diagnosis for skeletal disorders." (PMID 38062428, 2023). "The identification of the WDR19:c.878G>A variant as a contributing factor to adult-onset, typically nonsyndromic ESKD in the Druze population provides further evidence that the spectrum of ciliopathies is broader than traditionally perceived, extending beyond early-onset and multiorgan disease." (PMID 41141533, 2025). "It has been hypothesized that more severe WDR19 pathogenic variants may lead to multisystemic ciliopathies, while hypomorphic variants may be associated with non-syndromic retinal dystrophy (RP, macular dystrophy)." (PMID 36833218, 2023).
nephronophthisis (8 papers, 2021 to 2025). Progressive tubulointerstitial injury, inherited in an autosomal recessive pattern, caused by mutations in genes involved in ciliary function, which may result in an end stage renal failure. "WDR19 encodes a protein in the intraflagellar transport complex, and pathogenic variants are associated with a rare subtype of nephronophthisis called NPHP13." (PMID 40776899, 2025). "Mutations in WDR19 are associated with autosomal recessive cranioectodermal dysplasia 4 (MIM 614378), SRTD5 (MIM 4376), nephronophthisis 13 (MIM 614377) and Senior-Loken syndrome (MIM 616307)." (PMID 38062428, 2023). "The AOH segments harbored potential candidate genes associated with autosomal recessive conditions, such as nephronophthisis (NPHP1, WDR19, and TMEM67)." (PMID 37576556, 2023). "Of note, unlike many patients with nephronophthisis, who exhibit normal-sized or atrophic kidneys, tubular-specific WDR19 conditional knockout mice developed significantly enlarged kidneys, closely resembling the phenotype of autosomal dominant polycystic kidney disease." (PMID 41141533, 2025).
Sensenbrenner syndrome (7 papers, 2014 to 2025). "For example, Sensenbrenner syndrome (also known as cranioectodermal dysplasia), a ciliopathy characterized by sagittal craniosynostosis with accompanying facial, skeletal, and ectodermal anomalies, is caused by mutations in the IFT-A genes IFT43, WDR35, IFT122, WDR19, and IFT140." (PMID 28724397, 2017). "WDR19 (IFT144) localizes mainly at the ciliary tip and at the base of cilium, while in Sensenbrenner syndrome patients it is absent or mislocalized." (PMID 32276433, 2020).
Jeune syndrome (5 papers, 2013 to 2023). Jeune syndrome, also called asphyxiating thoracic dystrophy, is a short-rib dysplasia characterized by a narrow thorax, short limbs and radiological skeletal abnormalities including "trident" aspect of the acetabula and metaphyseal changes. "Further, mutations in additional IFT components including TTC21B/IFT139, DYNC2H1 and WDR19/IFT144 have been reported in association with Jeune syndrome." (PMID 24009529, 2013). "Yet, “mild” phenotypes seem to go beyond Sensenbrenner and Jeune syndromes, given the fact that mutations in the IFT genes TTC21B and WDR19 are also associated with isolated nephronophthisis." (PMID 22829176, 2013). "The genotypes of DYNC2H1, IFT172 and WDR19 and the phenotypes of the fetuses give hints for the diagnosis of short-rib thoracic dysplasia (SRTD) with or without polydactyly 3, 10, and 5, respectively." (PMID 38062428, 2023).
Senior Løken syndrome (4 papers, 2021 to 2023). "In a 22-year-old woman with retinal pigmentary changes, WDR19-related Senior-Løken syndrome was diagnosed." (PMID 33946315, 2021). "One example is WDR19 which is associated with JATD, CED, NPHP, RP, and Senior Løken syndrome." (PMID 35873489, 2022).
Caroli disease (2 papers, 2022 to 2025). Caroli disease (CD) is a rare congenital liver disease characterized by non-obstructive cystic dilatations of the intra-hepatic and rarely extra-hepatic bile ducts. "Other studies have suggested that mutations in the WDR19 gene can also lead to either Caroli disease or Caroli syndrome.Due to limited resources, none of the cases in this cohort underwent PKHD1 or ARPKD genetic testing." (PMID 41039418, 2025).
renal failure (2 papers, 2018 to 2025). "Variants in the WDR19 gene, a crucial component of the intraflagellar transport (IFT) complex A, are associated with renal-cystic ciliopathies, a prevalent cause of renal failure of genetic origin." (PMID 41141533, 2025).
retinal diseases (2 papers, 2023 to 2025). "Mutations in WDR19 have been linked to retinal diseases that can lead to blindness in humans and associated to adaptation for nocturnal vision of night herons." (PMID 39846218, 2025). "WDR19-associated retinal diseases are inherited in an autosomal recessive fashion." (PMID 36833218, 2023).
retinal dystrophies (2 papers, 2017 to 2023). "The study showed that the WDR19-Stargardt phenotype is within the phenotypic spectrum of ABCA4-Strgardt disease, stressing the importance of genetic testing in patients with inherited retinal dystrophies." (PMID 36833218, 2023).
Rod-cone dystrophy (2 papers, 2022 to 2023). An inherited retinal disease subtype in which the rod photoreceptors appear to be more severely affected than the cone photoreceptors. "WDR19 variants are mostly linked to RP (i.e., rod-cone dystrophy)." (PMID 36833218, 2023).
adult-onset renal failure (1 paper, 2025). "Our study validates the pathogenic role of the WDR19 hypomorphic variant in adult-onset renal failure and highlights how hypomorphic pathogenic variants disrupt kidney development." (PMID 41141533, 2025).
Ataxia (1 paper, 2022). Ataxia refers to impaired coordination of voluntary muscle movement. "Among the top 10 DMR genes, WDR19 was associated with ataxia, SYCP1 regulated the meiosis progress, FAM173B and CCT5 involved chronic pain." (PMID 36344488, 2022).
brain aneurysm (1 paper, 2023). A congenital or acquired aneurysm within the cranium. "Brain aneurysm was observed in eight patients (16%), and the causative genes were PKD1 (missense (n = 2), nonsense (n = 1)), PKD2 (missense (n = 1), splice-site (n = 1)), ZNF423 (missense), GLIS2 (missense) or PKHD1 (missense) or WDR19 (splice-site), and CEP164 (missense)." (PMID 36833371, 2023).
cervical cancer (1 paper, 2021). A primary or metastatic malignant neoplasm involving the cervix. "WDR19 and ITSN1 are also likely susceptibility genes of cervical cancer." (PMID 33403041, 2021). "Particularly, with regards to the four non-MHC genes, we observe that, besides WDR19, ITSN1 is also detected to be marginally related to cervical cancer (p = 0.081) in the EAS population." (PMID 33403041, 2021).
cutaneous melanoma (1 paper, 2020). A primary melanoma arising from atypical melanocytes in the skin. "In addition, hyperactive EZH2 mutations are reported to control cell growth and metastasis through silencing of distinct tumor suppressors, such as DCK, AMD1, and WDR19, in cutaneous melanoma." (PMID 32906688, 2020).
Kidney Cyst (1 paper, 2023). Abnormal fluid filled sac within the kidney, either acquired or congenital. "While DNAJB11 is a known disease-causing gene of ADPKD, and kidney cysts can develop in patients who are heterozygous for a pathogenic variant in PKHD1, more evidence is required to determine whether heterozygous NEK8 and WDR19 pathogenic variants can mimic the ADPKD phenotype." (PMID 36833371, 2023).
oral cavity tumors (1 paper, 2022). "Interestingly, three patients with oral cavity tumors (51.1, 207, and 339) presented gains encompassing WDR genes (WDR83, WDR19, and WDR47, respectively)." (PMID 36552033, 2022).
prostate carcinoma (1 paper, 2022). A carcinoma that arises from epithelial cells of the prostate gland. "The upregulation of WDR83 and WDR19 has been implicated in gastric and prostate cancers, respectively." (PMID 36552033, 2022).
Stargardt disease (1 paper, 2023). "Addition of WDR19 in the group of genes producing phenocopies of Stargardt disease underlines the importance of genetic testing and may help to understand its pathogenesis." (PMID 36833218, 2023). "Variants in WDR19 (IFT144) have been implicated as another possible cause of Stargardt disease." (PMID 36833218, 2023). "The addition of WDR19 to the group of Stargardt disease causing genes may help to understand the pathogenesis of this frequent, yet untreatable disease." (PMID 36833218, 2023).
cancer (3 papers, 2021). A tumor composed of atypical neoplastic, often pleomorphic cells that invade other tissues. "In-Patient 1, variants in FNIP1, PPP1R15A, WDR19, and RUNX3 were present in ~100% of cancer cells across all samples." (PMID 34400647, 2021).
kidney disease (3 papers, 2023 to 2025). "Moving forward, investigating how modulating the Shh and FGF8 signaling pathways counteract the effects of WDR19 variants may potentially offer promising therapeutic possibilities for this genetic kidney disease." (PMID 41141533, 2025). "Defects to the IFT-A complex of proteins (e.g., WDR35, IFT122, IFT43, IFT172, IFT140 and WDR19), can present with renal disease phenotypes such as chronic renal failure, NPHP, and renal cysts and, in some cases, isolated NPHP or NPHP-like nephropathy." (PMID 38292052, 2023).
WDR19 also shares sentences with these, for which no sentence is quoted: tumor (3 papers); autosomal dominant polycystic kidney disease (2); Bardet-Biedl syndrome (2); breast carcinoma (2); cystic kidney disease (2); Usher syndrome (2); Alport syndrome (1); Atrophy (1); Blindness (1); craniosynostosis (1); cyst (1); Dent disease (1); Fabry disease (1); genetic disease (1); Glomerular sclerosis (1); homocysteinemia (1); IgA nephropathy (1); kidney failure (1); Leber congenital amaurosis (1); liver cysts (1); Liver fibrosis (1); Lowe syndrome (1); Macular dystrophy (1); Methylmalonic aciduria (1); Pigmentary retinopathy (1); polydactyly (1); renal dysplasia (1); retinal degeneration (1); Senior-Loken syndrome 8 (1); speech disorder (1).
A further 1 disease shares a sentence with WDR19 in 1 paper.